TMEM145 (transmembrane protein 145)
Synonyms: FLJ90805
Tractability: Antibody: UniProt predicts a signal peptide or a membrane-spanning region. PROTAC: its protein half-life has been measured.
Gene: Protein-coding gene on chromosome 19 (42,313,309 to 42,325,064, forward strand). Ensembl gene ENSG00000167619.
Subcellular location: Membrane
Subcellular location (Human Protein Atlas): Vesicles
Gene Ontology:
Biological process: G protein-coupled receptor signaling pathway; response to pheromone
Cellular component: membrane
Genetic constraint (gnomAD): Loss-of-function variants: 46 observed, 69.39 expected, observed/expected ratio (o/e) 0.66, 90% interval 0.52 to 0.85. The upper end of that interval is the gene's LOEUF score, 0.85, which puts it in group 3 of 6, group 1 being the genes least tolerant of losing a copy. Missense variants: 551 observed, 626.75 expected, observed/expected ratio (o/e) 0.88, 90% interval 0.82 to 0.94. Synonymous variants: 248 observed, 265.82 expected, observed/expected ratio (o/e) 0.93, 90% interval 0.84 to 1.04.
Homologues: Orthologues: pig TMEM145 (96% identical), chimpanzee TMEM145 (96% identical), macaque TMEM145 (95% identical), dog TMEM145 (94% identical), mouse Tmem145 (94% identical), rat Tmem145 (94% identical), guinea pig TMEM145 (94% identical), tropical clawed frog tmem145 (77% identical), zebrafish tmem145 (69% identical), rabbit TMEM145 (65% identical), Caenorhabditis elegans tmem-145 (30% identical). Paralogues in human: GPR180 (19% identical).
Diseases named in the same sentence as TMEM145 in open-access papers:
TMEM145 is named in the same sentence as 5 diseases in open-access papers, as found by Europe PMC text mining. Sharing a sentence is not in itself a finding about the gene and the disease. The quoted sentences say what the papers report.
breast carcinoma (1 paper, 2025). "In oncology, its identification of spatially resolved therapeutic targets—such as VEGFA and CD74 in glioblastoma, or ARL2 and TMEM145 in breast cancer—highlights its potential to uncover microenvironment-specific drivers of disease progression." (PMID 41275376, 2025). "TMEM145 exhibits significantly high methylation status in all stages (I–III) of breast invasive ductal carcinoma, accompanied by upregulated gene expression, making it a potential epigenetic biomarker for breast cancer that may play a key role in cancer progression." (PMID 41275376, 2025).
Dementia with Lewy body (1 paper, 2022). "Interestingly, rs10423769 is reported to be a sQTL for TMEM145, which has not been implicated in AD, although it has been reported to be upregulated in anterior cingulate cortex in Dementia with Lewy body patients." (PMID 35788729, 2022).
TMEM145 also shares sentences with these, for which no sentence is quoted: breast invasive ductal carcinoma (1 paper); cancer (1); glioblastoma (1).